EGF (epidermal growth factor)
Diseases named in the same sentence as EGF in open-access papers (continued):
Sharing a sentence is not in itself a finding about the gene and the disease.
tumor (continued). "These TAMs reciprocally secrete factors such as EGF and FGF2, which polarize TAMs back to an anti‐tumor M1‐like phenotype and inhibit monocyte migration." (PMID 40904700, 2025). "At last, it was uncovered that the tumor growth and metastasis were relieved after FDX1 overexpression, but these changes were reversed after EGF treatment." (PMID 38520567, 2025). "By contrast, module 2 and 3, which were only downregulated in EGF-stimulated SHP2WT cells, contained several tumor suppressors, such as NRG1, MAP3K1, CAVIN3, EPHA3/7, CTNNA1/3, and NOTCH3." (PMID 40631144, 2025). "Mechanistically, tumor-derived CXCL1 activates TAMs via paracrine secretion, driving their M2 polarization and stimulating EGF secretion." (PMID 41445742, 2025). "The tumor microenvironment is rich in chemokines and cytokines, such as CXCL12 and EGF, that drive tumor progression and metastasis." (PMID 40796929, 2025). "EGF has an anti-apoptotic effect on tumor cells, and high ECF expression can induce tumor cell adhesion and metastasis." (PMID 41444284, 2025). "TAMs directly or indirectly affect tumor vasculature and participate in angiogenesis by secreting pro-angiogenic factors and inflammatory factors, including VEGF-A, MMP, EGF, TGF-β, and TNF-α." (PMID 40131539, 2025). "Platelets also enhance tumor angiogenesis by secretion of several proangiogenic factors like VEGF, platelet-derived growth factor, and epidermal growth factor." (PMID 40016853, 2025). "Multiple signaling pathways, including VEGF, EGF, FGF, and HGF, play pivotal roles in endothelial tube formation and angiogenesis within tumor tissues, contributing to the heterogeneity of blood vessel structures observed in cancer." (PMID 40371330, 2025). "Beyond, EGF, Notch, and JAK-STAT, we feel it will be pertinent to test the tumor suppressor BMP pathway as a potential mediator of Rel-dependent stem cell survival." (PMID 40964961, 2025). "Epidermal growth factor (EGF) signaling is the first step in activating glycolysis, and inhibition of EGF receptor (EGFR) inhibits cancer cell proliferation and tumor growth." (PMID 40309242, 2025). "At last, our results demonstrated that the tumor growth and metastasis were relieved after FDX1 overexpression, but these changes were rescued after EGF treatment." (PMID 38520567, 2025). "CAFs also secrete growth factors such as TGF-β, fibroblast growth factor (FGF), epidermal growth factor (EGF), and hepatocyte growth factor (HGF) to induce EMT-like CAMs and exacerbate the aggressiveness and resistance of tumor cells." (PMID 40510029, 2025). "The released extracellular TGF-β and EGF act on tumor cells to activate EMT, which increases cell invasion and metastasis and promotes tumor development and metastasis." (PMID 40943546, 2025). "During tumour growth, VEGF is secreted by the tumoural cells in response to diverse stimuli occurring around their microenvironment, including cytokines (such as EGF, FGF, IGF, PDGF), low pH, hypoxia and hypoglycaemia." (PMID 39753522, 2025). "ROSs, such as H2O2, elevate the expression or activity of proteins, such as matrix metalloproteinases (MMPs), vascular endothelial growth factor (VEGF), epidermal growth factor (EGF), and EGF receptor (EGFR), which are crucial in tumor metastasis." (PMID 40427390, 2025). "Specifically, macrophages secrete epidermal growth factor (EGF), which binds to epidermal growth factor receptors (EGFR) on tumor cells, activating downstream signaling pathways and inducing colony-stimulating factor 1 (CSF-1) secretion." (PMID 40547026, 2025). "FABP5 facilitates tumor cell proliferation and metastasis by modulating the PPAR β/δ signaling pathway and stabilizing epidermal growth factor." (PMID 40178066, 2025). "Growth factors such as EGF, VEGF, FGF, IL‐10, IL‐6, TNF‐α, IFNγ produced by TAMs and NKs and miRNAs carried in tumour‐derived EVs promote tumour proliferation by activating pathways such as RAS–RAF–MEK–ERK–MAPK and PI3K–AKT–mTOR." (PMID 40525649, 2025).
tumor (continued). "Its activation, driven by tumor-infiltrating microglia and macrophage-derived extracellular factors such as EGF, PDGFB, SDF-1α, IL-6, and IL-8, enhances tumor cell motility and survival." (PMID 40867240, 2025). "Intercellular communication analysis also indicated enhanced signaling of pro-tumor TNF, EGF, VEGF, FGF, and WNT among cells in the NT5E-positive group." (PMID 41487509, 2025). "Our study also identified enhanced EGF, MK, TWEAK, and HGF signaling between high-glycan-score tumor cells and others." (PMID 40861802, 2025). "This enzymatic remodeling releases growth factors (e.g., TGF‐β and EGF) sequestered within the ECM, activating cognate receptor tyrosine kinases on tumor cells." (PMID 40904700, 2025). "The tumor size, volume, and weight were all relieved after FDX1 overexpression, but these changes were reversed after EGF treatment (p < 0.001)." (PMID 38520567, 2025). "It secretes a range of growth hormones, cytokines, and chemokines that support the survival and multiplication of tumor cells, including VEGF, prostaglandin E2 (PGE2), CCL17, IL-6, TNF-α, and epidermal growth factor (EGF)." (PMID 40230883, 2025). "Further components are soluble factors, including growth factors such as epidermal growth factor (EGF), VEGF, and platelet-derived growth factor (PDGF), which play a vital role in enhancing angiogenesis, tumour cell proliferation, and metastasis." (PMID 40906384, 2025). "TAMs within spheroids can secrete epidermal growth factor (EGF), resulting in the downstream upregulation of EGFR and VEGF signaling that promote tumor cell proliferation and migration." (PMID 41280929, 2025). "GSCs obtained from tumor dissociation were transfected with GFP and cultured in an NBE medium (NeurobasalTM medium with B27, N2, EGF, and bFGF)." (PMID 41226697, 2025). "A study showed that numerous cytokines in follicular fluid such as insulin-like growth factors (IGF), epidermal growth factor (EGF) and transforming growth factor-β (TGF-β) induce tumor cell proliferation and invasion." (PMID 40045411, 2025). "Further information flow analysis identified increased expression of PECAM1, EGF, VISFATIN, ANNEXIN, and LAMININ in the high‐ac4C group, molecules known to play critical roles in tumor initiation, progression, and metastasis." (PMID 40767620, 2025). "They promote tumor growth through paracrine signaling (e.g., TGF-β, FGF, EGF, HGF), activate proliferative pathways (MAPK, PI3K/AKT), and remodel the extracellular matrix to support expansion." (PMID 40732242, 2025). "Tetrameric ACAT1 is commonly upregulated in cells stimulated by EGF, and, in diverse human cancer cells, inhibition of tetrameric ACAT1 attenuated tumor growth." (PMID 40166933, 2025). "The protein product of AREG is a ligand for the EGF/TGF-α receptor with connection to EMT, increased tumor cell migration and proliferation, and has been reported as a prognostic biomarker for treatment targeting EGFR in other cancer entities." (PMID 40082664, 2025). "In various tumor cell lines, endogenous RHBDL2 activity has been observed, where it cleaves EGF just outside its transmembrane domain, promoting its secretion and triggering EGFR activation." (PMID 40668798, 2025). "As central regulators of tumor angiogenesis, TAMs secrete key pro-angiogenic factors, such as VEGF, EGF, PDGF, TGF-β, and angiopoietins, and facilitate perivascular ECM breakdown via matrix metalloproteinase release." (PMID 41417432, 2025). "TC tumor cells expressed receptors for multiple signaling pathways, including MK, PTN, SPP1, TWEAK, EGF, and IFN-II (IFNG) (blue frames)." (PMID 41228323, 2025). "This vaccine stimulates the production of antibodies that bind to EGF, thereby inhibiting the activation of EGFR and reducing tumor growth." (PMID 40859900, 2025). "EGF is one of the ligands of EGFR, and its binding to EGFR activates downstream signaling pathways that promote tumor cell proliferation and survival." (PMID 40859900, 2025).
tumor (continued). "Analysis of ligand-receptor pairs revealed interactions between CXCR1+ neutrophils and tumor cells involving TGFA-EGFR and EGF-EGFR, potentially explaining aspects of resistance to third-generation EGFR-TKIs due to sustained EGFR activation." (PMID 39638994, 2024). "TAMs also secrete growth factors, including PDGF, EGF, TGF-β, and hepatocyte growth factors (HGF) to induce the proliferation and invasion of tumor cells." (PMID 39003350, 2024). "Second, M2-type TAMs promote angiogenesis; M2-type TAMs are a major source of epidermal growth factor (EGF), which is a direct promoter of tumor growth." (PMID 39403370, 2024). "The expression of TSLP when stimulated with EGF in U251 cell line and GBM-b cells suggests a potential contribution of GBM to the immunomodulation of the tumor microenvironment, through the production of TSLP, in line with previous reports in different tumors." (PMID 38557942, 2024). "Platelets contribute by releasing growth factors, such as PDGF, EGF, and VEGF, inducing tumor angiogenesis and enhancing blood vessel permeability through the release of MMPs, 5-hydroxytryptamine, and histamine." (PMID 38732051, 2024). "As for VEGFA + tumor/epithelial cells, the major outgoing signals were WNT, EGF, and VEGF, while the main incoming signals involved numerous signaling pathways, including COLLAGEN." (PMID 38200479, 2024). "EGF and CSF1 induce the formation of invadopodia in tumor cells and podosomes in TAMs, structures that break the ECM and facilitate intravasation." (PMID 39003350, 2024). "MDSCs also express FGF-2, PDGF, IL-1β, IL-28/IFN-λ, TGFβ, EGF, and HGF that can stimulate EC proliferation and migration, contributing to tumor angiogenesis." (PMID 38580870, 2024). "A screen of signaling patterns predicted strong signaling interactions between TREM1 myeloid cells and BIT tumor epithelium, with candidate TREM1 myeloid cell-derived signals including EGF, VISFATIN, IL1, TGF-β, and OSM." (PMID 39289380, 2024). "Upon activation, CAFs can release a range of soluble factors that can enhance tumor invasion and metastasis, such as TGF-β, hepatocyte growth factor (HGF), epidermal growth factor (EGF), FGF and IL-6 cytokine." (PMID 39139454, 2024). "Epidermal growth factor receptor (EGFR)-mediated activations of MAPK, PI3K, and STAT3 signaling pathways demonstrate important mechanisms by which various ligands (i.e., EGF, TGF-α, amphiregulin, etc.)influence tumor growth, survival, and metastasis." (PMID 38539448, 2024). "PLT can secrete growth factors like epidermal growth factor (EGF) and vascular endothelial growth factor (VEGF), promoting tumor cell proliferation and angiogenesis." (PMID 39606245, 2024). "The tumour area activated various proliferation and metastasis‐related signalling pathways (such as MK, SEMA3, MIF, ANGPT, EGF and VEGF)." (PMID 39187937, 2024). "HES1 expression was upregulated by IL-4, EGF, TGF-β, and other factors, consistent with earlier reports, including studies showing that tumor-CM contain Hes1-inducing factors." (PMID 39702544, 2024). "In vitro and in vivo migration assays and intravital imaging show that tumor cells and macrophages migrate through the TME together using a CSF1/EGF paracrine loop that leads to invasion and metastasis." (PMID 39555068, 2024). "It has also been documented that growth factors, e.g., EGF and HGF, induced tyrosine phosphorylation of β-catenin in several tumor cell lines." (PMID 38727316, 2024). "TAMs contribute to tumor cells migration and invasion by reshaping the extracellular matrix and releasing mediators like VEGF, PDGF, and EGF." (PMID 38834662, 2024). "Cetuximab blocks the binding of epidermal growth factor to its receptor, inhibiting the EGFR signaling pathway critical for tumor growth and survival." (PMID 39123466, 2024).
tumor (continued). "In contrast, M2 TAMs suppress inflammation while promoting tissue repair, remodeling, and tumor angiogenesis through the release of vascular endothelial growth factor (VEGF), epidermal growth factor (EGF), and fibroblast growth factor (FGF)." (PMID 39531417, 2024). "EGF is released by tumor cells and binds to the EGF receptor (EGFR) on tumor ECs to promote EC migration and capillary tube formation." (PMID 38892305, 2024). "TG2, stimulated by Epidermal Growth Factor (EGF) through the Ras and c-Jun kinase pathways, facilitates the motility and invasive capacity of tumor cells." (PMID 38474044, 2024). "ANG plays dual roles in promoting tumour cell proliferation and angiogenesis in tumour growth and is also an essential permissive factor for VEGF, aFGF, bFGF, and EGF in promoting angiogenesis." (PMID 38421827, 2024). "This process is mediated via a paracrine loop involving tumor-synthesized CSF1 and macrophage-produced EGF that drives the migration of tumor cells toward blood vessels." (PMID 39516356, 2024). "Conversely, in tumor samples, intercellular interactions were predominantly active in COLLAGEN, WNT, CXCL, TGFb, and EGF signaling pathways." (PMID 38702814, 2024). "On the other hand, various cell factors produced by NEU, such as epidermal growth factor, vascular endothelial growth factor, and transforming growth factor-β (TGF-β), promoted angiogenesis and tumor cell growth." (PMID 38540104, 2024). "TAMs secrete vascular endothelial growth factor (VEGF), platelet-derived growth factor (PDGF), epidermal growth factor (EGF), etc., which are involved in peritumor angiogenesis and promote tumor infiltration and metastasis." (PMID 38263363, 2024). "Co-administration of excess EGF to block EGFR on normal tissues further decreased uptake in liver, kidneys and spleen but decreased tumour uptake (1.4% ID/g)." (PMID 38703297, 2024). "The expression and activity of MMP9 are regulated by various tumor-related factors, including TGF-β, EGF, and FGF, which participate in the regulation of multiple signaling pathways involved in tumor initiation and progression." (PMID 38769413, 2024). "TAM can then secrete IL-10, GF-β, EGF, WNT, etc. to influence the signal transduction pathway in tumor cells, leading to the proliferation and metastasis of tumor cells." (PMID 38602556, 2024). "Exosomes promote cancer progression by transporting various growth factors, such as epidermal growth factor (EGF), VEGF, and fibroblast growth factor (FGF), to the tumor microenvironment." (PMID 39886659, 2024). "Cell therapy with rCD8+ T-cells reduced the amount of Axl+, Axl+CD117+, CD117+ EGF+CD44+PD-L1+PD-1+ and CD117+CD44+ cells in the lungs of mice with spontaneously metastatic tumor." (PMID 38664641, 2024). "The secretion of epidermal growth factor (EGF) by CAFs maintains ITGA5 expression and sustains aggregates formed by CAFs and ascites tumor cells." (PMID 38491511, 2024). "EGF was shown to increase TRPM7 expression and function, and TRPM7 was suggested to be critically involved in the EGF-induced migration of tumor cells." (PMID 38255793, 2024). "Because changes in cytoskeletal dynamics in tumor cells can correlate with the EMT, which can be triggered by TGFβ/EGF used in the cellular assays in our report, we analyzed the requirement for SWAP-70 for the expression of EMT markers by several approaches." (PMID 38760173, 2024). "In this sense, TAMs enhance OC metastasis by secreting epidermal growth factor (EGF), which promotes sphere formation and tumor growth." (PMID 37039909, 2023). "Moreover, limited stability and early release of labelled iodine from their conjugated VHH before reaching their target protein might limit clinical usefulness, as was shown for the application of 125I-labelled EGF in an in vivo model of an EGFR overexpressing tumor." (PMID 37746282, 2023).
tumor (continued). "Combining both EGF- and VEGF-loaded microcapsules within the vascularized tumor model produced metastatic dissemination of tumor cells with modulated sprouting angiogenesis." (PMID 37241602, 2023). "In turn, tumor cells secrete numerous factors such as transforming growth factor-β (TGF-β), epidermal growth factor (EGF) and C-X-C motif chemokine ligand 12 (CXCL12), which can activate and educate CAFs." (PMID 36717783, 2023). "The M2 cells' secretion of cytokines such as IL10, EGF, and VEGF can inhibit T cell proliferation and promote tumor growth and angiogenesis." (PMID 38110895, 2023). "They discovered that tumor-educated LECs secreted amounts of epidermal growth factor (EGF) and PDGF-BB to promote tumor growth." (PMID 36632469, 2023). "The stronger protective effect of FGF1 than EGF against taltobulin and its effect on MCF-7 cell migration suggests its particular relevance in tumor progression and drug resistance." (PMID 37509496, 2023). "HNSCC tumor cells produce IL-6, CXCL8, and EGF, which improve the survival and angiogenic potential of endothelial cells through the activation of the STAT3/AKT/ERK signaling pathways." (PMID 38003931, 2023). "In addition, inflammatory cells within the tumor microenvironment may contribute to the production of tumor-promoting molecules, such as growth factors, pro-angiogenic cytokines, and enzymes that can promote invasion (e.g., CSF-1, EGF, VEGF, and MMP-9)." (PMID 36672343, 2023). "CAFs also express vascular endothelial growth factor (VEGF), platelet-derived growth factor (PDGF), interleukin (IL)-8, epidermal growth factor (EGF), and fibroblast growth factor 2 (FGF-2), ultimately forming a tumour growth supporting microenvironment." (PMID 38041196, 2023). "This process is regulated by transcription factors in tumor cells (Snail 1, Slug, ZEB1, Twist, FOXC2, etc.)and signaling pathways from the tumor microenvironment (WNT, Notch, Hedgehog, TGFβ, FGF, EGF, HGF signaling, etc.)." (PMID 38139030, 2023). "M2 macrophages also produce EGF and vascular endothelial growth factor A (VEGFA) to promote tumour growth and angiogenesis." (PMID 37612278, 2023). "In addition to their role in immunosuppression and tumor growth promotion, M2-like TAMs can release a wide range of cytokines that promote tumor cell proliferation and survival, including epithelial growth factor (EGF), platelet-derived growth factor (PDGF), and transforming growth factor-β (TGF-β)." (PMID 37138860, 2023). "Low passage tumor alone secreted high concentrations of CCL2/MCP1, CXCL8/IL-8, CXCL1/GRO, IL-6, CXCL10/IP10, G-CSF, TGFβ1, MMP1, CCL3/MIPα, GM-CSF and EGF." (PMID 37063842, 2023). "Several tumor-derived molecules, such as transforming growth factor (TGFβ), fibroblast growth factor (FGF), epidermal growth factor (EGF), hedgehogs, Wnt ligands, and interleukin-6 (IL-6), act as EMT inducers." (PMID 37046817, 2023). "Production of EGF by macrophages promoted tumor growth by EFGR signaling in tumor cells, triggering VEGF release by tumor cells and autocrine VEGFR signaling." (PMID 36658699, 2023). "In multiple tumor cell lines, STP has been shown to be a much more potent inhibitor of EGF-driven cellular proliferation than gefitinib." (PMID 36903565, 2023). "With regard to functional characteristics, CAFs produce growth factors such as epidermal growth factor (EGFR) and VEGF and also produce matrix metalloproteinases (MMPs), which are involved in the remodeling of the ECM and promote tumor growth and metastasis." (PMID 38003931, 2023). "M2 macrophages release epidermal growth factor, chemokines (such as CCL24and CCL22), and cytokines (such as TNF-α and IL-6) that directly promote tumor growth and metastasis and promote tumor progression." (PMID 37153586, 2023).